RNU6-1006P (RNA, U6 small nuclear 1006, pseudogene)
Gene: Small nuclear RNA gene on chromosome 2 (170,119,996 to 170,120,098, reverse strand). Ensembl gene ENSG00000252807.
Homologues: Orthologues: chimpanzee U6 (99% identical), macaque U6 (80% identical), mouse Gm54512 (49% identical). Paralogues in human: RNU6-1152P (76% identical), RNU6-211P (76% identical), RNU6-428P (76% identical), RNU6-480P (76% identical), RNU6-144P (75% identical), RNU6-16P (75% identical), RNU6-310P (75% identical), RNU6-753P (75% identical), RNU6-1145P (74% identical), RNU6-116P (74% identical), RNU6-196P (74% identical), RNU6-247P (74% identical), and 1285 more.